SLC46A3 (solute carrier family 46 member 3)
Description:
Lysosomal proton-coupled steroid conjugate and bile acid transporter. Preferentially recognizes lipophilic steroid conjugates or bile acis as endogenous substrates and seems to mediate escape from lysosomes to the cytoplasm. Modulates hepatic cytosolic copper homeostasis, maybe acting as a lysosomal copper transporter and sequestering copper ions in the lysosome (By similarity). Transports catabolites of non-cleavable antibody-drug conjugates from the lysosome to the cytoplasm. Delivers pathogen-associated molecular patterns to cytosolic pattern recognition receptors as part of the innate immune response to microbes. Selectively transports bacterial muramyl dipeptide (MDP) into the cytosol for recognition by NOD2, triggering inflammatory responses (By similarity). Likely acts as a redundant importer of cyclic GMP-AMP dinucleotides (cGAMPs) in monocyte and macrophage cell lineages. The transport mechanism, its electrogenicity and stoichiometry remain to be elucidated (Probable).
Synonyms: FKSG16; DKFZp686A1775; FLJ42613
Tractability: Antibody: UniProt predicts a signal peptide or a membrane-spanning region; the Human Protein Atlas places it where antibodies can reach. PROTAC: its protein half-life has been measured.
Gene: Protein-coding gene on chromosome 13 (28,700,064 to 28,719,012, reverse strand). Ensembl gene ENSG00000139508.
Subcellular location: Lysosome membrane
Subcellular location (Human Protein Atlas): Cytosol; Plasma membrane; Actin filaments
Gene Ontology:
Molecular function: transmembrane transporter activity; copper ion transmembrane transporter activity
Biological process: vacuolar transmembrane transport; cellular response to 2,3,7,8-tetrachlorodibenzodioxine; copper ion transmembrane transport; transmembrane transport
Cellular component: extracellular exosome; lysosomal membrane
Genetic constraint (gnomAD): Loss-of-function variants: 27 observed, 41.24 expected, observed/expected ratio (o/e) 0.65, 90% interval 0.48 to 0.9. The upper end of that interval is the gene's LOEUF score, 0.9, which puts it in group 3 of 6, group 1 being the genes least tolerant of losing a copy. Missense variants: 510 observed, 571.86 expected, observed/expected ratio (o/e) 0.89, 90% interval 0.83 to 0.96. Synonymous variants: 185 observed, 203.31 expected, observed/expected ratio (o/e) 0.91, 90% interval 0.81 to 1.03.
Homologues: Orthologues: chimpanzee SLC46A3 (99% identical), macaque SLC46A3 (95% identical), dog SLC46A3 (87% identical), pig SLC46A3 (81% identical), rabbit SLC46A3 (76% identical), mouse Slc46a3 (75% identical), guinea pig SLC46A3 (71% identical), rat Slc46a3 (66% identical), tropical clawed frog slc46a3 (43% identical), zebrafish SLC46A3 (43% identical), zebrafish slc46a3 (39% identical). Paralogues in human: SLC46A1 (30% identical), SLC46A2 (25% identical).
Diseases named in the same sentence as SLC46A3 in open-access papers:
SLC46A3 is named in the same sentence as 10 diseases in open-access papers, as found by Europe PMC text mining. Sharing a sentence is not in itself a finding about the gene and the disease. The quoted sentences say what the papers report.
breast carcinoma (5 papers, 2020 to 2025). "Loss of SLC46A3 increases the resistance of HER2+ breast cancer to trastuzumab emtansine." (PMID 39199284, 2024). "We identified seven potential genes within breast cancer: NOL4, STAR, C8G, NEIL1, SLC46A3, FRMD6, and SCARF2." (PMID 39199284, 2024). "Through differential expression analysis and mutual information, we identified seven genes (NOL4, STAR, C8G, NEIL1, SLC46A3, FRMD6, and SCARF2) that are potential biomarkers in breast cancer." (PMID 39199284, 2024).
multiple myeloma (2 papers, 2020 to 2021). "There was a wide range of SLC46A3 expression in multiple primary myeloma cells, including several samples with undetectable levels." (PMID 34358100, 2021). "The study revealed that SLC46A3-negative multiple myeloma cells were resistant to BCMA-targeting ADCs with DM1 and PBD, but were sensitive to those with MMAF." (PMID 34358100, 2021).
Hepatic steatosis (1 paper, 2021). Steatosis is a term used to denote lipid accumulation within hepatocytes. "In conclusion, TG accumulation by TCDD is induced by the induction of lysosome SLC46A3, which causes mitochondrial dysfunction by intracellular copper deficiency leading to hepatic steatosis." (PMID 33436590, 2021). "In view of the effects of TCDD on hepatic steatosis, it was of interest to determine whether SLC46A3 expression and its induction by AhR, affects hepatic lipid levels." (PMID 33436590, 2021).
hepatocellular carcinoma (1 paper, 2021). A malignant tumor that arises from hepatocytes. "In hepatocellular carcinoma, increased expression of SLC46A3 inhibited cell proliferation, migration, and invasion." (PMID 34977043, 2021).
lung carcinoma (1 paper, 2022). "Thirty one down-regulated genes are known to be prognostic markers of lung cancer, 28 of which are of favorable prognosis, such as GDPD1, SLC46A3, CLIC6, LZTS3 or CCNO." (PMID 36544755, 2022).
cancer (6 papers, 2014 to 2025). A tumor composed of atypical neoplastic, often pleomorphic cells that invade other tissues. "Although the biological function of SLC46A3 in cancer is not yet fully understood, its reported relationship with lipid catabolism likely explains its strong influence on liposomal NP uptake." (PMID 40536233, 2025). "And SLC46A3 is an effective transporter of the cytotoxic drug maytansine, which is used in antibody-based targeting cancer cells." (PMID 36686439, 2022). "Specifically, the study highlights the discovery of SLC46A3, a solute carrier (SLC) transporter localized to the lysosome, as a negative regulator of liposomal NP uptake, which could influence NP accumulation and delivery in cancer cells." (PMID 40536233, 2025).
tumor (4 papers, 2020 to 2021). "Among them, ZIC1 and SLC46A3 have been shown to function as tumor suppressors and ZIC1 was found to play an important role in the Wnt/β-catenin pathway and EMT." (PMID 34930906, 2021). "The expression of SLC46A3 (FKSG16) was downregulated in around 80% of human HCC tissues compared to non-tumor adjacent tissues, while tumors that expressed low levels of SLC46A3 had more aggressive phenotypes and shorter survival times after surgery." (PMID 32549224, 2020).
SLC46A3 also shares sentences with these, for which no sentence is quoted: cardiovascular disease (1 paper); invasive ductal carcinoma (1); muscular disease (1).